PABPN1 (poly(A) binding protein nuclear 1)
Diseases named in the same sentence as PABPN1 in open-access papers (continued):
Sharing a sentence is not in itself a finding about the gene and the disease.
cancer (continued). "In this study, we revealed PABPN1’s pivotal involvement in oncogenesis and the progression of tumors across many types of cancer." (PMID 40607380, 2025). "The reduced nuclear localization of QKI likely diminishes its ability to promote PABPN1 LLPS in cancer cells, as validated by overexpression of QKI and QKI-NLS, and further supported by the effect of arsenite treatment." (PMID 40052530, 2025). "The correlations with TMB, MSI, neoantigens, and ESTIMATE scores underscore the potential significance of PABPN1 in shaping the immune landscape of various cancers, contributing to our understanding of its role in the broader context of cancer immunotherapy." (PMID 40607380, 2025). "The primary objective of this study was to uncover the potential of PABPN1 in anticancer immunotherapy for human cancers, thereby providing insights into a novel antitumor strategy." (PMID 40607380, 2025). "By validating the cancer-related factors and pathways targeted by PABPN1, we determined the role of PABPN1 as a regulator of Wnt signaling, cell cycle, and lipid biosynthesis." (PMID 36879298, 2023). "Deletion of PABPN1 induces APA events, leading to microRNA-mediated gene regulation and causing the release of cancer cells." (PMID 34899345, 2021). "PABPN1 has been proven to be the master factor regulating APA profiles across multiple cancer types in a large TCGA cohort 37, which supports the efficacy of our proliferation screening system." (PMID 32929364, 2020). "The PABPN1–NEXT–exosome pathway thus represents one possibility of how nuclear polyadenylated lncRNAs, among them also cancer-associated lncRNAs like TUG1 and NEAT1, are targeted for degradation." (PMID 32340118, 2020). "These outcomes suggested that PABPN1 may played a significant role in fostering oncogenesis and advancing tumor progression in human cancers." (PMID 40607380, 2025). "This approach holds the potential to enhance our understanding of PABPN1’s role in cancer immunity and could lead to the creation of effective therapeutic strategies." (PMID 40607380, 2025). "However, there has been limited systematic analysis of the role of PABPN1 in prognosis and immunology across many human cancers." (PMID 40607380, 2025). "This implied a potential role for PABPN1 in the growth and progression of these cancers." (PMID 40607380, 2025). "This substantiated PABPN1’s potential as a pan-cancer prognostic biomarker." (PMID 40607380, 2025). "Subsequently, we delved into the ESTIMATE score of PABPN1 across many cancer types." (PMID 40607380, 2025). "All these findings collectively suggested that PABPN1 may play a crucial role in the onset and progression of cancer in urogenital tissues." (PMID 40607380, 2025). "We further examined whether the inhibitory effects of QKI-6 on cancer cell proliferation and migration depend on PABPN1 LLPS." (PMID 40052530, 2025). "In non-small cell lung cancer, the dysregulation of PABPN1 may contribute to tumor aggressiveness by potentially releasing cancer cells from microRNA-mediated gene regulation." (PMID 40607380, 2025). "Previous studies have demonstrated that PABPN1 significantly influences the progression of KIRC, suggesting that targeting PABPN1 may offer a new therapeutic strategy for this cancer." (PMID 40867324, 2025). "Hence, it is essential to undertake a prospective study focusing on PABPN1 expression and its involvement in immune infiltration in human cancers." (PMID 40607380, 2025). "In summary, our hypothesis suggested that PABPN1 could serve as a potential pan-cancer biomarker or a novel immunotherapy target, with the potential to predict the response to immunotherapy." (PMID 40607380, 2025).
cancer (continued). "The findings revealed a notably elevated expression of PABPN1 across many cancer types." (PMID 40607380, 2025). "The functions of PABPN1 through modulating APA patterns have been investigated in human cancers." (PMID 36879298, 2023). "Altogether, NEAT1 is an excellent example of a cancer-associated lncRNA, which is collectively regulated by multiple RBPs that can either enhance its stability (HuR and SRSF1) or promote its degradation (AUF1 and PABPN1)." (PMID 32340118, 2020). "In particular, PABPN1 shows significant higher expression in HPV positive cancers." (PMID 31039132, 2019). "Furthermore, high PABPN1 expression in certain cancers, especially OV, may serve as an indicator of favorable therapeutic efficacy in immunotherapies targeting ICP genes." (PMID 40607380, 2025). "Furthermore, PABPN1 expression varied within different immune subtypes of one cancer type." (PMID 40607380, 2025). "In light of this, we delved into the connections between PABPN1 expression and ICP genes across human cancers, aiming to uncover the potential role of PABPN1 in immunotherapy." (PMID 40607380, 2025). "The expression of PABPN1 in BLCA, LIHC and BRCA tissues was significantly higher than that in para-carcinoma tissues." (PMID 40607380, 2025). "The second cluster (rightmost group) includes relevant cancer types such as COAD or READ and shares the enrichment of PABPN1 and NOL12, both of which are related to tumor progression." (PMID 39595158, 2024). "However, the role of PABPN1 in cancer progression and development remains unknown." (PMID 32153636, 2020). "By combining miRNA profiles with global APA site states in CRC patients, we found miRNAs appeared to regulate APA by modulating APA regulators such as NUDT21 and PABPN1, whereas APA regulated cancer-related gene expression by inducing 3'UTR alteration." (PMID 32153636, 2020). "We observed a reduction in the LLPS of PABPN1 but not in its expression level in cancer cells and identified SNRPD2 and SNRNP70 as regulators of its phase separation." (PMID 40052530, 2025). "Our investigation revealed that PABPN1 expression did not consistently exhibit a negative correlation with TILs across different human cancers." (PMID 40607380, 2025). "These may suggest that longer transcripts of PABPN1, CCDC12 and ISY1 are important for maintaining cancer cell survival (p < 0.01)." (PMID 36263133, 2022). "PABPN1, a suppressor of APA, might suppress tumor aggressiveness by releasing cancer cells from microRNA-mediated gene regulation and was higher in the low-risk group." (PMID 34512654, 2021). "Because TNBC is a highly proliferative cancer, we reasoned that TNBC cell lines might be sensitive to changes in the CPSF1 and PABPN1 levels." (PMID 32929364, 2020). "The varying relationships between PABPN1 expression and gene markers of immune cell infiltration in LIHC, BLCA, and TGCT may contribute to the distinct survival outcomes observed in different cancer types." (PMID 40607380, 2025). "Thirdly, despite our conclusion that PABPN1 expression was significantly correlated with immune cell infiltration and cancer prognosis, there was a lack of direct evidence demonstrating PABPN1’s direct influence on prognosis through participation in immune infiltration." (PMID 40607380, 2025). "The expression of PABPN1 tended to be higher in human cancers compared to paired normal tissues." (PMID 40607380, 2025). "A pan-cancer bioinformatic analysis found PABPN1 expression significantly correlates with distal PAS usage in many types of human cancer, suggesting it may broadly promote usage of distal APA sites in cancer." (PMID 32560344, 2020).
tumor (11 papers, 2015 to 2025). "To further elucidate the potential functional role of PABPN1 in tumor tissue, we investigated PABPN1 coexpression networks using the LinkedOmics database." (PMID 40607380, 2025). "In this study, we demonstrated for the first time that PABPN1 functions as a tumor suppressor in BC." (PMID 36879298, 2023). "In vivo assays showed that overexpression of PABPN1 in BC cells significantly reduced tumor volume and weight of the subcutaneous xenografts, while knockdown of PABPN1 increased the tumor-initiating ability of BC cells." (PMID 36879298, 2023). "RIP and qRT-PCR analysis also showed that the binding of HuR to multiple target mRNAs (including PABPN1 mRNA) was significantly inhibited in tumor cells with higher circPABPN1 expression." (PMID 36091137, 2022). "In this study, we performed shRNA pooled library screening and identified CPSF1 and PABPN1 as key C/P factors involved in tumor proliferation." (PMID 32929364, 2020). "The obtained results provided additional confirmation supporting the hypothesis that PABPN1 may impact antitumor immunity through the regulation of the composition and immune mechanisms within the tumor microenvironment." (PMID 40607380, 2025). "These correlations supported the hypothesis that PABPN1 may exert an influence on antitumor immunity by regulating the composition and immune mechanisms within the tumor microenvironment." (PMID 40607380, 2025). "In this study, we identified PABPN1 as a tumor suppressor in BC." (PMID 36879298, 2023). "In conclusion, our study identifies PABPN1 as a tumor suppressor in BC." (PMID 36879298, 2023). "In addition, we established CPSF1 and PABPN1 as key C/P factors involved in tumor proliferation and APA regulation in TNBC." (PMID 32929364, 2020). "Knockout of CPSF1 or PABPN1 reverses APA events of tumor-related genes in TNBCs, inhibits tumor cell proliferation, promotes apoptosis and redistributes the cell cycle." (PMID 34899345, 2021). "Furthermore, a pooled shRNA library screening identified CPSF1 and PABPN1, two alternative C/P factors, as potential targets of TNBC linking APA to tumor proliferation." (PMID 32929364, 2020).
myopathy (3 papers, 2016 to 2022). A disease of the muscle in which the muscle fibers do not function properly. "An expansion mutation in PABPN1 is the genetic cause of oculopharyngeal muscle dystrophy (OPMD), a late onset and rare myopathy." (PMID 27152426, 2016). "An alanine expansion mutation in the N-terminus of PABPN1 is the genetic cause of OPMD, a late-onset myopathy." (PMID 27152426, 2016). "The sample included 16 participants with PEO (8 associated with single mtDNA deletion, including 3 KSS; 8 with mutations in POLG), nine with OPMD with mutations in PABPN1, and nine controls without histological or clinical evidence of myopathy." (PMID 33352713, 2020).
neurodegenerative disease (3 papers, 2024 to 2025). A disorder of the central nervous system characterized by gradual and progressive loss of neural tissue and neurologic function. "SERBP1-associated proteins contain several factors involved in neurological disorders and neurodegenerative diseases, including FMR1, SMN1, and PABPN1." (PMID 39937575, 2025).
metabolism disorders (1 paper, 2023). "Furthermore, circPABPN1 inhibited the binding of HuR to PABPN1 mRNA, and therefore circPABPN1 reduced the translation of its host gene PABPN1 mRNA by competing with the translation activator (HuR), thus leading to metabolism disorders and tumorigenesis." (PMID 37060016, 2023).
PABPN1 also shares sentences with these, for which no sentence is quoted: ptosis (5 papers); muscle disorder (3); female infertility (2); amyloidosis (1); amyotrophic lateral sclerosis (1); anal carcinoma (1); B-cell lymphoma (1); Blepharophimosis (1); blood cancer (1); bone cancer (1); brain cancer (1); Camptocormia (1); cardiomyopathy (1); cholangiocellular carcinoma (1); cleidocranial dysplasia (1); colorectal adenocarcinoma (1); congenital central hypoventilation syndrome (1); dilated cardiomyopathy (1); esophagus cancer (1); Facioscapulohumeral dystrophy (1); gastric cancer (1); genetic disorder (1); head and neck cancer (1); Huntington disease (1); infantile spasm syndrome (1); influenza (1); Intellectual disability (1); Kennedy disease (1); kidney cancer (1); leukemia (1).
A further 13 diseases each share a sentence with PABPN1 in 1 paper.